RASSF1 (Ras association domain family member 1)
Description:
Potential tumor suppressor. Required for death receptor-dependent apoptosis. Mediates activation of STK3/MST2 and STK4/MST1 during Fas-induced apoptosis by preventing their dephosphorylation. When associated with MOAP1, promotes BAX conformational change and translocation to mitochondrial membranes in response to TNF and TNFSF10 stimulation. Isoform A interacts with CDC20, an activator of the anaphase-promoting complex, APC, resulting in the inhibition of APC activity and mitotic progression. Inhibits proliferation by negatively regulating cell cycle progression at the level of G1/S-phase transition by regulating accumulation of cyclin D1 protein. Isoform C has been shown not to perform these roles, no function has been identified for this isoform.
Synonyms: RDA32; NORE2A; REH3P21; 123F2; RASSF1A
Tractability: PROTAC: ubiquitination databases record sites on it; its protein half-life has been measured.
Gene: Protein-coding gene on chromosome 3 (50,329,782 to 50,340,980, reverse strand). Ensembl gene ENSG00000068028.
Subcellular location: Cytoplasm, cytoskeleton (Isoform A); Cytoplasm, cytoskeleton, microtubule organizing center, centrosome; Cytoplasm, cytoskeleton, spindle; Cytoplasm, cytoskeleton, spindle pole; Nucleus; Nucleus (Isoform C)
Gene Ontology:
Molecular function: protein binding; zinc ion binding; small GTPase binding
Biological process: Ras protein signal transduction; signal transduction
Cellular component: microtubule cytoskeleton; nucleus; centrosome; cytoskeleton; spindle; spindle pole
Genetic constraint (gnomAD): Loss-of-function variants: 33 observed, 31.33 expected, observed/expected ratio (o/e) 1.05, 90% interval 0.8 to 1.41. The upper end of that interval is the gene's LOEUF score, 1.41, which puts it in group 5 of 6, group 1 being the genes least tolerant of losing a copy. Missense variants: 445 observed, 429.15 expected, observed/expected ratio (o/e) 1.04, 90% interval 0.96 to 1.12. Synonymous variants: 191 observed, 173.76 expected, observed/expected ratio (o/e) 1.1, 90% interval 0.98 to 1.24.
Homologues: Orthologues: chimpanzee RASSF1 (99% identical), pig RASSF1 (95% identical), dog RASSF1 (94% identical), mouse Rassf1 (91% identical), rat Rassf1 (90% identical), guinea pig RASSF1 (90% identical), macaque RASSF1 (68% identical), tropical clawed frog rassf1 (64% identical), zebrafish rassf1 (44% identical), Drosophila melanogaster Rassf (16% identical). Paralogues in human: RASSF5 (43% identical), RASSF3 (28% identical), RASSF4 (20% identical), RASSF2 (16% identical), RASSF6 (16% identical).
Diseases named in the same sentence as RASSF1 in open-access papers:
RASSF1 is named in the same sentence as 255 diseases in open-access papers, as found by Europe PMC text mining. Sharing a sentence is not in itself a finding about the gene and the disease. The quoted sentences say what the papers report.
breast cancer (171 papers, 2004 to 2026). A primary or metastatic malignant neoplasm involving the breast. "Detailed analysis of the RASSF1 promoter (RASSF1‐1α vs RASSF1‐2γ) in early‐stage breast cancer supports the association of RASSF1C with adverse prognosis and offers an optimized biomarker for patients." (PMID 34532864, 2021). "Hypermethylation of the RASSF1 gene has been widely associated with poor prognostic outcome in breast cancer patients." (PMID 34532864, 2021). "In another candidate gene study of normal breast tissue, the same group observed that RASSF1 methylation is associated with breast cancer risk level, and that increasing parity is associated with decreased APC methylation." (PMID 28693600, 2017). "RASSF1 has been previously associated with Her2 status and promoter hypermethylation has been showed to have prognostic values in early stage breast cancer." (PMID 25068292, 2014). "explored the hypothesis that RASSF1 encoded a tumor suppressor gene in lung and breast cancer, and found that RASSF1A was a potential tumor suppressor gene in lung and breast cancer." (PMID 36875059, 2023). "The results support the hypothesis that high methylation of RASSF1‐1α, indicating reduced RASSF1A expression, is moderately associated with poor breast cancer outcome (P = 0.045, log‐rank test)." (PMID 34532864, 2021). "We selected RASSF1, previously demonstrated to be aberrantly methylated in liquid biopsies from breast cancer patients, as our gene of interest." (PMID 36648833, 2023). "Although methylation of the RASSF1 gene has been investigated in a large number of clinical studies and has been considered as a potential biomarker for breast cancer progression, how methylation of RASSF1‐2γ influences disease outcome has not been addressed." (PMID 34532864, 2021). "RASSF1 has been reported to be hypermethylated in breast cancer and showed a similar pattern to the reference control in breast cancer patients from both the Taiwan and Western cohorts." (PMID 33803633, 2021). "RASSF1 promoter hypermethylation is also reported in osteosarcoma, breast cancer, upper aerodigestive tract cancer, glioma, clear cell carcinoma of the kidney, urothelial carcinoma, thyroid carcinoma, and neuroblastoma." (PMID 34885067, 2021). "In general, breast cancer patients that were alive at follow‐up had lower median methylation of RASSF1‐1α, in agreement with the tumor suppressor role of RASSF1A, than those stages I and II patients that had died of breast cancer." (PMID 34532864, 2021). "Although RASSF1 has been reported to be hypermethylated in breast cancer patients, it showed a similar pattern in breast cancer patients from both the Taiwan and Western cohorts and was used as the reference control." (PMID 33803633, 2021). "In contrast, somatic hyper-methylation of RASSF1 was reported in > 4% of endometrial cancers and > 1% of breast cancers." (PMID 32859265, 2020). "Overall, CST6, HOXB4, ITIH5 and RASSF1 were more frequently methylated in CTCs from breast cancer patients compared to MNCs from healthy controls." (PMID 29190932, 2017). "Another most commonly inactivated gene in various cancers, Ras association domain-containing protein 1, RASSF1, undergoes either DNA methylation or chromosomal deletion in breast cancer." (PMID 26884818, 2016). "Conversely, there are many reports about the possible role of RASSF1 hypermethylation as a biomarker in breast cancer related to pathological characteristics of worse prognosis, but almost nothing is known about its involvement in breast cancer subtypes." (PMID 26284587, 2015).
breast cancer (continued). "Our objectives were to analyze the presence of methylation of the less-studied RASSF2 gene in breast cancer subtypes, along with the well-known gene RASSF1, and to evaluate the prognostic role of these alterations in patients." (PMID 26284587, 2015). "Accordingly, we detected high levels of CGI methylation for APC, HIC1 and RASSF1 in the breast carcinoma cell line MCF-7_wt and for APC and HIC1 in the doxorubicin sensitive cell line OVCAR-5." (PMID 20544021, 2010). "Kaplan–Meier curve analysis showed that neither DNMT1 nor RASSF1 high expression was significantly associated with OS or disease-specific survival in breast cancer patients (log-rank P > 0.05)." (PMID 41381440, 2025). "Taken together, our findings suggest that assessment of the methylation status of both RASSF1‐1α and RASSF1‐2γ promoters can be a refined tool for breast cancer patient stratification and concurs to provide a more sensitive prognostic signature than the use of RASSF1‐1α methylation alone." (PMID 34532864, 2021). "Furthermore, our previous experiment using the same animal model focused on the epigenetic modulation of clove buds and showed a demethylation effect on the promoter of the RASSF1 tumor suppressor in mammary tumors in vivo." (PMID 31323834, 2019). "Furthermore, Feng and colleagues (2007) analyzed the methylation of multiple genes in breast cancer using bisulfite pyrosequencing and found that RASSF1 was methylated in 58 % of breast tumors, CDH13 in 44 % and RARB in 17 %." (PMID 27065772, 2016). "Furthermore, promoter hyper-methylation of APC and RASSF1 has been demonstrated to be a significant prognostic factor for the survival of breast cancer patients." (PMID 20544021, 2010). "Inverse association between methylation of RASSF1 and BRCA1 loci and lower level of vitamin B12 is translated to clinical setting and it could be a useful public health strategy to decrease the risk of breast cancer." (PMID 27775595, 2016). "In breast cancer, BRCA1 has been reported as a target of UHRF1-mediated methylation, while in non-small-cell lung cancer, RASSF1, CYGB, and CDH13 have been identified as UHRF1-regulated methylation targets." (PMID 41373864, 2025). "Recently, the methylation status in the RASSF1 promotor was analyzed by modified COBRA protocols with the Microfluidics Electrophoresis (LabChip) for accessible and rapid breast cancer screening." (PMID 38982390, 2024). "Methylation at many gene promoters has been reported to have independent prognostic value in breast cancer including HOXA11, ESR1 and PITX2, HOXD13 CDH22 BRCA1 and RASSF1." (PMID 33461604, 2021). "Five of these genes were found to be significantly methylated in breast cancers from our cohort in Senegal (APC, RASSF1, GASTP1, SCGB3a1, and HS3ST2)." (PMID 31819783, 2019). "The five most frequently methylated TSGs (RASSF1, APC, CDH13, GSTP1, and CDKN2B) were the same in all groups of breast cancer and, with the exception of CDKN2B, were involved in other tumors from LS patients, too, although with variable frequencies." (PMID 22691310, 2012). "However, poorer sensitivity or specificity in plasma for the early detection of breast cancer was found for the LOC643719, ENPP2, ADCY4 and RASSF1 genes." (PMID 33803633, 2021). "In addition, breast cancer patients with high expression of ATAT1 and MAPK8, RASSF1, BCL2, CXCL8, and FGF1, had a poor prognosis." (PMID 34199510, 2021). "For example, women without breast cancer, but at high risk (Gail model score) are more likely to have aberrant methylation of the tumor suppressor genes APC and RASSF1 compared with women at low risk." (PMID 28693600, 2017).
breast cancer (continued). "Within hypermethylated c-HMRs, we detected previously reported frequent DNA hypermethylation at gene promoters such as MGMT in glioblastoma, NSD1 in neuroblastoma, ESR1 in breast cancer, GSTP1 in prostate cancer and the promoter hypermethylation of RASSF1 in various cancer contexts." (PMID 28581523, 2017). "We found that methylation of RASSF1-1α (representing gene silencing) significantly correlates with low pS127-YAP1 in glioma, bladder, and breast cancer cohorts, suggesting that YAP1 may be nuclear and active in RASSF1-methylated tumors." (PMID 26549256, 2015). "RASSF1, CDH1 and HIC1 are frequently silenced due to hypermethylation in breast cancer patients." (PMID 25068292, 2014). "The most frequently methylated genes were RASSF1 (65%), APC (43%), CDH13 (35%), GSTP1 (17%), and CDKN2B (17%), and the pattern was quite similar in breast carcinomas from mutation carriers, non-carriers and sporadic ductal cases." (PMID 22691310, 2012). "In this study, aberrant methylation of RASSF1, APC and GSTP1 were both frequent as well as early events in the progression continuum from normal to benign to invasive cancer and support a monoclonal transformation continuum to breast cancer progression." (PMID 21776373, 2011). "Also, overexpression of the DNA methyltransferase, DNMT3B, was identified in lung and breast cancer cell lines and depletion of DNMT3B expression in breast cancer cell line was shown to activate the methylated RASSF1; therefore, we analysed the expression of these factors by qRT-PCR." (PMID 21712824, 2011).
lung carcinoma (165 papers, 2004 to 2026). "The detection of methylation patterns in Short Stature Homeobox 2 (SHOX2) and Ras-association domain family member 1A (RASSF1A) have been preliminarily used for the diagnosis of lung cancer." (PMID 35837113, 2022). "Methylation of L1RE1, RARB, and RASSF1 serve as potential biomarkers for the differential diagnosis of lung cancer." (PMID 36741260, 2023). "Our laboratory focuses on the oncogenic activities of the Ras Association Domain Family Member 1 (RASSF1) gene in breast and lung cancer." (PMID 36826019, 2023). "The methylation of L1RE1, RARB, and RASSF1 acts as potential disease specific biomarkers for predicting the prognosis of lung cancer." (PMID 32218699, 2020). "Our recent study involving a murine model of inflammation-induced lung cancer analogously revealed early epigenetic changes within tumor suppressor genes Rassf1, Cdh13, and Dapk1." (PMID 33396408, 2020). "Promoter hypermethylation of RASSF1 was reported as a frequent event in lung cancer and the highest methylation (up to 100%) was found in SCLC." (PMID 29851970, 2018). "RASSF1 hypermethylation is another frequent event in lung cancer affecting approximately 60% of adenocarcinomas (ADC) and up to 100% of small cell lung carcinomas (SCLC)." (PMID 29851970, 2018). "Growth effects of the SARAH domain of RASSF1 were investigated in stable transfected lung cancer cells." (PMID 22577552, 2012). "It is interesting therefore that RASSF1 DNA methylation has been found in the sputum of smokers prior to the detection of overt lung cancer." (PMID 21731750, 2011). "Numerous groups have reported RASSF1 DNA methylation in lung cancer, and methylation of this gene has been associated with poor prognosis and later stage cancer." (PMID 21731750, 2011). "Overexpression of RASSF1 induces cell cycle arrest in lung carcinoma cell line H1299." (PMID 37353691, 2023). "Hypermethylation of multiple genes can occur simultaneously in a tumor, such as APC, DKPK1, MGMT, P16, and RASSF1 in lung cancer, while others, like RASSF1 and P16, could be hypermethylated in a variety of tumors." (PMID 37077808, 2022). "Thus, this may explain how RASSF1 methylation and tumour stiffness contribute to poor outcome in lung cancer patients, by reducing differentiation status and inducing pluripotency." (PMID 31268606, 2019). "It is hypothesised that RASSF1 acts as a tumor suppressor in lung cancer progression." (PMID 22768131, 2012). "Within the validation dataset (27 lung cancer cases and 38 benign controls) L1RE1, RARB, and RASSF1 were analyzed successfully." (PMID 29851970, 2018). "L1RE1 in combination with either RARB or RASSF1 could function as biomarkers for separating lung cancer and non-cancerous tissue and could be useful for samples of limited size such as biopsies." (PMID 29851970, 2018). "With 269 novel interactions, OncoPPi greatly expands the landscape of interactions among this selected set of lung cancer genes and defines interactions with potential significance for cancer PPI target discovery, such as CDK4/STK11, LATS2/RASSF1 and MYC/NSD3 (WHSC1L1)." (PMID 28205554, 2017).
prostate carcinoma (53 papers, 2006 to 2025). A carcinoma that arises from epithelial cells of the prostate gland. "A previous study measuring DNA methylation at GSTP1, APC, and RASSF1 loci in repeat prostate biopsies identified AA and EA men at risk of high-grade prostate cancer." (PMID 38566104, 2024). "GSTP1, APC, and RASSF1 are three candidate tumor suppression genes, inactivated by hypermethylation, which have been implicated in higher-risk prostate cancers." (PMID 39202766, 2024). "The ConfirmMDx, which is based on the evaluation of the promoter methylation levels of three genes, namely GSTP1, APC and RASSF1 in prostate biopsy samples, was designed to identify men at lower risk for prostate cancer, thus avoiding repeated biopsies." (PMID 37511475, 2023). "For example, in prostate cancer, the fifth major cause of cancer-related mortality globally, hypermethylation of certain tumour suppressor genes, such as GSTP1, RARB, APC and RASSF1, has been observed during the early stages of the disease." (PMID 39661598, 2024). "The capability of the BMMs is demonstrated to appositely model the beta values, to objectively identify thresholds and to identify existing and novel DMCs, including those related to genes implicated in prostate cancer, such as GSTP1, RARB and RASSF1." (PMID 39661598, 2024). "On performing gene ontology analysis, CpG sites in cluster 2 were found to be related to known genes e.g., RARB, GSTP1, RASSF1, SFRP2, which are implicated in prostate cancer." (PMID 39661598, 2024). "For example, researchers can rapidly detect fluctuations in prostate cancer-related epigenetic biomarkers (RASSF1, APC, and RARb gene hypermethylation) before and after drug administration." (PMID 37304140, 2023). "For example, the integrated analysis function of the prostate cancer organoids-on-a-chip can rapidly detect fluctuations in prostate cancer-related epigenetic biomarkers (RASSF1, APC, and RARb gene hypermethylation) before and after drug administration." (PMID 37304140, 2023). "This test evaluates the methylation status of several genes known to be frequently found in prostate cancer: Glutathione S-Transferase Pi 1 (GSTP1), Adenomatous Polyposis Coli (APC), and Ras association domain family member 1 (RASSF1)." (PMID 36768533, 2023). "We have shown that prostate carcinoma-associated epigenetic biomarkers including GSTP1, RASSF1﻿, RARb and APC are detectable in our cultures to confirm that these primary PDCOs indeed originated from tumor cells." (PMID 34581895, 2021). "Methylation of five candidate genes frequently silenced by methylation in breast and prostate cancer, including ER, RARβ2 and the cell cycle regulators p16, RASSF1 and CCND2 (cyclin D2) was analyzed in breast tissue." (PMID 25322458, 2014). "APC and RASSF1 have also been described as prostate cancer markers with important roles in detecting the epigenetic field effect surrounding cancer foci." (PMID 22672250, 2012). "In the present report, a diagnostic tissue-based test for prostate cancer presence consists of the epigenetic statuses of 3 genes, i.e. GSTP1APC and RASSF1, in addition to one control gene, ACTB, used to quantitate amplifiable DNA." (PMID 22672250, 2012). "Biomarkers like GSTP1, APC and RASSF1 have demonstrated involvement with prostate cancer, with the latter two genes playing prominent roles in the field effect." (PMID 22672250, 2012). "Numerous studies have found that RASSF1 is a potential biomarker for the diagnosis of lung, cervical, and prostate cancer, implying that our assay and primers could be effective in screening for other diseases." (PMID 36648833, 2023). "High-throughput strand-specific RNA-seq of poly(A)+ RNA from LNCaP prostate cancer cells showed transcription from the plus strand in the RASSF1 locus, and the assembly of these RNA-seq reads using the Cufflinks tool generated a consensus sequence mapping to the genomic plus strand in the locus." (PMID 23990798, 2013).